CD36 (CD36 molecule (CD36 blood group))
Diseases named in the same sentence as CD36 in open-access papers (continued):
Sharing a sentence is not in itself a finding about the gene and the disease.
tumor (continued). "Particularly, the CD36 expression by immunosuppressive cells such as Tregs and MDSCs in the tumor suggests its contribution to the immunosuppressive function of these cell types in the tumor-bearing hosts." (PMID 39273384, 2024). "Important molecules involved in the lipolysis, transport, and uptake of exogenous fatty acids include the fatty acid binding protein 4 (FABP4), the fatty acid tissue translocase CD36, and the angiopoietin-like protein 4 (ANGPTL4), which have all been recently implicated in tumor biology." (PMID 39456610, 2024). "Consistent with this, CD36 expression was correlated with tumor grade." (PMID 39624081, 2024). "Building upon a recent study that unveiled the pivotal role of CD36 in regulating ferroptosis among tumor-infiltrating CD8+ T cells, the present study further identified the critical function of CD36 in mediating ferroptosis in CD4+ T cells, specifically within the context of ATAAD." (PMID 39266539, 2024). "However, in contrast to tumor cells, the expression of CD36 is downregulated in tumor microvessels and stroma." (PMID 38276607, 2024). "CD36 gene expression in CD8 + TILs gradually increases with tumor growth." (PMID 38302980, 2024). "High CD36 expression in tumor tissues is correlated with poor survival in various cancer types." (PMID 39402302, 2024). "Additionally, CD36 is known to support Treg activity and survival within the tumour microenvironment." (PMID 36816957, 2023). "Moreover, CD36 induced reprogramming of the lipid uptake in tumor cells, tumorigenesis, and metastasis." (PMID 36726488, 2023). "Also, a study on a mouse model with a genetic knockout of CD36 has shown as decrease in the infiltration of Treg cells into the tumor site, but the levels of infiltrated antitumor T cells increased." (PMID 36624636, 2023). "Therefore, concentrated CD36 in Treg cells probably inhibits the metabolic fitness of Tregs in the tumor microenvironment and improves tumor prognosis." (PMID 36624636, 2023). "These phenotypes appear to be regulated via CD36-mediated FA uptake since xenograft tumor growth and metastasis are enhanced by HFD and could be attenuated by CD36 function blocking antibodies." (PMID 37371076, 2023). "Notably, AMPKα1 deletion reduced the expression of markers of anti-inflammatory M2 macrophages Ym1, Mannose receptor C-type 1 (MRC1), CD36, CD301 and Glutamine synthetase (GS), as well as CD169, a marker for M2-like tumour-associated macrophages." (PMID 36586434, 2023). "Increased expression of CD36 in tumor-infiltrating CD8+ T cells might induce lipid peroxidation, causing functional impairments in these T cells." (PMID 38562992, 2023). "Furthermore, the high expression of CD36 can promote tumor growth and tumor metastasis by regulating the Src/PI3K/AKT signal pathway or activating the Wnt/TGF-β signal pathway." (PMID 38264667, 2023). "Interestingly, in tumor cells, an acidic environment upregulates CD36 and DGAT expression, promoting exogenous lipid uptake and the formation of LDs, thereby promoting metastasis through a TGF-β2-dependent mechanism." (PMID 37700339, 2023). "Our results suggested that CD36 could be a potential immune checkpoint to recover the immune response against tumor, and CD36 blockage combined with chemotherapy would improve the survival of NSCLC patients." (PMID 37085798, 2023). "In addition, CD36 inhibitors can promote the submission of tumor-related antigens by DCs, decrease the amount of Treg cells, and promote the development of CD8+T cells." (PMID 38264667, 2023). "Increased CD36 expression levels in CD8+ T cells allows the accumulation of lipid peroxides in cells and leads to the decreased secretion of cytotoxic factors, causing the dysfunction of tumor-infiltrating CD8+ T cells." (PMID 37545500, 2023). "CD36 blockage may enhance anti-tumor response and therapeutic effects of chemotherapy in NSCLC patients." (PMID 37085798, 2023).
tumor (continued). "Moreover, we revealed that CD36+ myoepithelial cells were the tumour-initiating cells (TICs) in PA, and were dominated by the PI3K-AKT pathway." (PMID 37679344, 2023). "CD36-mediated intracellular lipid accumulation activates the PPARβ signaling pathway, which regulates mitochondrial metabolism and further enhances the immunosuppressive function of Treg cells in tumor." (PMID 37700339, 2023). "Decreased CD36 expression might contribute to tumor cell evasion from the immune system and targeting CD36 may be a potential therapeutic strategy in cancer immunotherapy." (PMID 38025525, 2023). "Similarly, CD36 inhibitor SSO synergizes with anti-PD-1 immunotherapy by restoring anti-tumor T cell responses in HCC." (PMID 37700339, 2023). "Therefore, targeting CD36 in Treg cells can be an effective approach to restore effective anti-tumor immune responses." (PMID 37700339, 2023). "CD36 also functions as a regulator of tumor-infiltrating Tregs." (PMID 37545500, 2023). "In addition to functioning as a FA transporter in cancer cells, CD36 also acts as a conduit for crosstalk with other cell types of the tumor microenvironment (TME), namely adipocytes, which supply FAs for cancer cell uptake." (PMID 37371076, 2023). "It was worth mentioning that CD36 expression in the mature and closely aligned tumor cells located inside the tumor body, that is, those cancer cells most probably under necrosis in the tumor, was significantly reduced." (PMID 37612265, 2023). "However, inhibition of FA synthase enhances CD36 expression, increasing tumor growth in various CRC models." (PMID 38186579, 2023). "In an effort to further illuminate the significance of CD36 repression in the development of a tumor-supportive stroma, we uncovered a broader impairment of PPARγ-activated transcriptional programs affecting several stromal cell types, including pericytes, ECs, and adipocytes." (PMID 37816052, 2023). "Interaction with stromal populations in the tumor microenvironment (TME) may be an important factor in modulating CD36 and CSC/EMT marker expression in cancer cells." (PMID 37371076, 2023). "SCD1 and CD36 knockdown suppressed tumor growth, whereas miR-3180 inhibitor promoted it." (PMID 37041584, 2023). "Moreover, SCD1 and CD36 knockdown abolished anti-miR-3180-induced tumor growth, suggesting that miR-3180 regulates tumor growth through these enzymes." (PMID 37041584, 2023). "Furthermore, targeting CD36 or CPT1 in combination with immunotherapy has shown promising results in enhancing anti-tumor immune responses." (PMID 37700339, 2023). "CD36 expression increased in PM samples compared with their primary tumor counterparts (p < 0.05)." (PMID 36042102, 2023). "Additionally, CD36 activity has been found to induce ferroptosis in tumor-infiltrating CD8+ T cells." (PMID 37977221, 2023). "Therefore, Rac1 activity enhanced by PA through the CD36-Src-Akt signaling pathway played the key role in mediating actin-remodeling and promoting tumor metastasis." (PMID 37612265, 2023). "We previously reported CD36 loss in the stroma of mammographically dense breast tissue, which is associated with a higher risk of IBC development, suggesting that CD36 loss can precede the development of a detectable invasive tumor." (PMID 37816052, 2023). "However, no research was conducted in NSCLC to explore the expression and distribution of CD36 in tumor-infiltrating T lymphocytes." (PMID 37085798, 2023). "Notably, an increased lipid accumulation and high CD36 expression in splenic NK cells isolated from surgery-treated tumor-bearing mice were observed." (PMID 37700339, 2023). "This suggests that CD36 may lead to inferior response to chemotherapy in NSCLC patients by impairing anti-tumor immune functions." (PMID 37085798, 2023). "As CD36 was demonstrated to promote tumor metastasis, we will focus on CD36 in the following study." (PMID 37207149, 2023).
tumor (continued). "In addition to the increase in lipogenesis pathways, tumor cells also prioritize the uptake of fatty acids through specific transmembrane receptors such as CD36, resulting in the accumulation of lipids." (PMID 37469457, 2023). "Similarly, upregulation of CD36 in natural killer (NK) cells also impairs their tumor-killing activity through intracellular lipid accumulation." (PMID 37700339, 2023). "The therapeutic strategy on targeting CD36 and CD36-Src-Akt/ERK signaling may have effective inhibitory effects on LUAD tumor growth and metastasis." (PMID 37612265, 2023). "However, the extent of CD36-mediated metabolic rewiring across cancer types or how this process contributes to tumor progression and drug resistance remains to be fully elucidated." (PMID 37371076, 2023). "The S100A4/PPARγ pathway enhances CD36-mediated FA uptake and thus the pro-tumor activity of TAMs." (PMID 37004014, 2023). "There is considerable interest in the potential roles of CD36 in tumor biology." (PMID 35438721, 2022). "Furthermore, we identified a CD36-dependent uptake of miR-200c, derived from apoptotic tumor cells, into macrophages." (PMID 35336722, 2022). "Almost all functions of CD36 have been found to be relevant to GBM tumor progression." (PMID 35054787, 2022). "CD36-driven lipid metabolic reprogramming and lead to tumor immune tolerance." (PMID 35785165, 2022). "CD36 can promote tumor angiogenesis through vascular mimicry (VM)." (PMID 36354702, 2022). "CD36 is a critical receptor for regulating lipid metabolism in tumor microenvironment cells and promoting tumor growth and metastasis; therefore, CD36 may become a potential biomarker for clinical diagnosis/prognosis as well as a target for cancer therapy." (PMID 35054787, 2022). "The role of CD36 in regulating tumor microangiogenesis has been confirmed in recent years in multiple ways, but some recent reports have unraveled new insights into the action of CD36 in regulating tumor vasculature." (PMID 36354702, 2022). "However, the CD36 downstream signaling pathways activated in each tumor type remain to be described." (PMID 36568966, 2022). "Selective targeting of CD36 on Treg cells may achieve better inhibition of tumor progression and better protection of immune homeostasis than the elimination of Treg cells." (PMID 36354702, 2022). "They found that CD36 was linked to higher-grade tumours and more advanced disease stage, but not to survival." (PMID 35159947, 2022). "Thus, CD36 can promote the fusion of macrophages with tumor stem cells to form THCs, making the tumor highly aggressive." (PMID 36354702, 2022). "Targeting the tumor-macrophage metabolic interface via CD36 inhibition may be an effective treatment strategy against liver metastasis." (PMID 36184646, 2022). "Because inflammation triggers the initiation, proliferation, invasion, and metastasis of tumor cells, reducing CD36-mediated sterile inflammation may become a new mode of anti-tumor treatment." (PMID 36591255, 2022). "Further research on the mechanism by which CD36 regulates tumor vasculature may enable the development of safe and effective anti-tumor drugs." (PMID 36354702, 2022). "Raised circulating fatty acid concentration in the tumour microenvironment might in some cases also reduce the numbers of tumour-infiltrating CD8+ T cells by inducing iron-dependent cell death (ferroptosis) via CD36." (PMID 36038791, 2022). "Given that CD36 is expressed extensively in other pro-tumor immune cells like regulatory T cells, the inhibition of CD36 may be a potential adjunct strategy to immunotherapy." (PMID 36172157, 2022). "In CLL, CD36 expression is higher in tumor samples than in healthy individuals’ samples." (PMID 36568966, 2022). "Therefore, improvement of disorder lipid metabolism by blocking CD36 is an effective therapeutic strategy for inhibiting tumor development, which deserves to be expected in clinical transformation." (PMID 35896782, 2022).
tumor (continued). "Those cancer cell experiments show that CD36 plays a key role in altered tumor metabolism." (PMID 35743814, 2022). "Indeed, in Lewis lung tumor-bearing mice, this metabolic feature is driven by tumor-derived G-CSF and GM-CSF, that promote the CD36-mediated FA uptake in tumor-infiltrating MDSCs." (PMID 35945203, 2022). "A study found that cholesterol in the tumor environment can increase the CD36 expression of CD8+ T cells and then ingest too many fatty acids, leading to lipid oxidative damage and iron death, further resulting in the loss of its lethal function and promoting the growth of tumors." (PMID 35295857, 2022). "In addition, CD36 promotes the integration of TAMs with tumor stem cells to make up extremely aggressive tumor-hybrid cells (THCs)." (PMID 36354702, 2022). "To determine whether host CD36 affects the extravasation of tumor cells, we labeled LLC cells with CMFDA and monitored their presence in the liver." (PMID 36184646, 2022). "The fatty acid receptor CD36 on the surface of the cells is responsible for lipids uptakes from the extracellular microenvironment to promote fatty acid oxidation, potentially activating tumour progression and metastasis." (PMID 35735113, 2022). "However, there is a paucity of studies exploring the relationship between CD36 and tumor VM and further research is required to investigate the specific mechanisms." (PMID 36354702, 2022). "CD36 expression in the tumor microenvironment is also a key component of tumor progression." (PMID 35991116, 2022). "In addition, lipid peroxidation and ferroptosis induced by CD36 inhibited the production of cytotoxic cytokines in tumor‐infiltrating CD8+ T cells." (PMID 36317423, 2022). "Targeting tumor ferroptosis-related metabolism through the intervention of CD36 may be an effective strategy for improving the anti-tumor efficacy of CD8+ T lymphocyte immunotherapy, which provides a new option for clinical treatment." (PMID 35619718, 2022). "In the present study, we evaluated whether CD36 in tumor cell-extrinsic microenvironment could influence liver metastasis." (PMID 36184646, 2022). "Metastatic tissue showed an enhanced CD36 expression in KM12L4a cell-derived metastatic tumour than in KM12SM cell-derived metastatic tumour, which would support the higher significant changes in the in vitro cell-based assays for KM12L4a cells than for KM12SM cells." (PMID 35957902, 2022). "It is suggested that CD36 may bind to TSP-2 to promote tumor angiogenesis through the MAPK signaling pathway." (PMID 36354702, 2022). "Moreover, it’s shown that the overexpression of CD36, which is the fatty acid (AA) transporter on T cells, can lead to tumor-infiltrating CD8+ T cell ferroptosis through excessive lipid peroxidation and eventually impaired anti-tumor immunity." (PMID 35432318, 2022). "The evidence demonstrates that CD36 participates in maintaining stemness and tumor growth progression and that oxLDL, not only FA as reported for other cancer cell types, might trigger relevant CD36 mediated signals." (PMID 36568966, 2022). "Blocking CD36 effectively suppresses tumor growth and prevents Tregs’ dysfunction." (PMID 36172157, 2022). "In addition, when lipid uptake is impeded following CD36 deletion, it has been observed that tumor-infiltrating Tregs are specifically impaired." (PMID 35406621, 2022). "Additionally, chemical inhibition of ERK5 or MEK5, the upstream MAPKK in the ERK5 pathway, decreased CD36 levels in the plasma membrane in several tumor cells." (PMID 35563698, 2022). "CD36 also plays an important role in regulating tumor angiogenesis." (PMID 36354702, 2022). "Importantly, an anti-PD-1 mAb combined with anti-CD36 mAb or CD36−/− Treg or CD36−/− CD8+ T cells display additive effects in suppressing tumor growth." (PMID 39872079, 2022). "An anti-CD36 antibody exhibits significant anti-tumor activity in human melanoma cells." (PMID 35743814, 2022).
tumor (continued). "This study: 1) proposes the existence of metabolic heterogeneity in LSC; 2) finds a role of CD36+ LSC in tumor progression; and 3) suggests that FA metabolism modulation may contribute to eradicating LCS." (PMID 36568966, 2022). "Furthermore, tumor immune tolerance and cancer growth are attributed to CD36-driven lipid metabolic reprogramming and functions in tumor-associated immune cells." (PMID 35682652, 2022). "In vivo, CD36 overexpressing cells display increased tumor growth kinetics and metastatic ability." (PMID 36568966, 2022). "Up-regulation of CD36 is also one of the reasons why tumor cells develop drug resistance." (PMID 36106108, 2022). "Moreover, a trend toward lymph node involvement in CD36-positive tumours, especially in earlier disease stages (pT1-T3; p = 0.101), was also observed." (PMID 35159947, 2022). "Blocking CD36 can inhibit tumor growth and metastasis in prostate cancer models." (PMID 35978815, 2022). "While compelling evidence exists to support CD36’s role in the promotion of primary tumor growth and progression in several cancers, some evidence also suggests that CD36 may also play a critical role in cancer metastasis." (PMID 35008415, 2022). "In addition, FABP4 secreted by CAA actively transports FA to tumor cells and the elevated expression of the FA transport proteins such as CD36 and FABP5, leading to an amplified transport of FA to tumor cells and boosting their proliferation." (PMID 36551752, 2022). "CD36 has been shown to be expressed in various cell types such as adipocytes, platelets, mononuclear macrophages, microvascular endothelial cells, myocardial cells, dendritic cells, hepatocytes, and tumor cells." (PMID 36354702, 2022). "CD36 has been related to cell proliferation and tumor growth kinetics in several types of cancers." (PMID 36568966, 2022). "Therefore, selective depletion of CD36 in Tregs suppressed tumor growth, decreased intratumoral Treg cells, and enhanced the anti-tumor activity in tumor-infiltrating lymphocytes without distrusting the immune homeostasis." (PMID 35371055, 2022). "DCA induced CD36 mRNA and plasma membrane CD36 protein in a large range of tumor cell lines." (PMID 35563698, 2022). "Additionally, FAO inhibition with etomoxir or CD36 deletion in TAMs slows tumor growth and M2 polarization." (PMID 35406621, 2022). "This study suggests that CD36 inhibition could represent a valid therapeutic tool for limiting tumor aggressiveness." (PMID 35625629, 2022). "Moreover, the expression of CD36 protein and the number of CD36-dependent metastasis-initiating tumour cells (CD44HCD36H) were reduced about twofold when the cells were exposed to CAP, DOX, LIN and TIG." (PMID 35768510, 2022). "As expected, the blockade of CD36 inhibited lipid deposition in tumor-treated macrophages." (PMID 36184646, 2022). "Inhibition of the STAT3 or STAT5 signaling pathway or deletion of the fatty acid transpose CD36 gene inhibits the activation of oxidative metabolism and induction of immunosuppressive function in tumor infiltration MDSCs and leads to delays in tumor growth dependent on CD8+ T cells." (PMID 36106333, 2022). "DCA increased CD36 mRNA expression of human tumor cells in vivo." (PMID 35563698, 2022). "The number of intratumoral Treg cells is reduced in Treg-specific Cd36-deficient mice with tumor grafts, which is associated with an increased amounts of CD8+ and CD4+FoxP3- tumor-infiltrating lymphocytes (TILs) and reduced tumor growth." (PMID 36568966, 2022). "In addition, CD36 can promote tumor cell adhesion to the extracellular matrix (ECM) and induce epithelial mesenchymal transition (EMT)." (PMID 36354702, 2022). "CD36 might be mediating the paracrine tumor-growth stimulation by adipocytes, since adipocytes promote OvCa growth and metastasis through the provision of FA." (PMID 36568966, 2022). "The role of CD36 in tumor progression supports its importance as a therapeutic target." (PMID 36568966, 2022).